NOX4 (NADPH oxidase 4)
Diseases named in the same sentence as NOX4 in open-access papers (continued):
Sharing a sentence is not in itself a finding about the gene and the disease.
tumor (continued). "We evaluated the subcellular localization of NOX4 by confocal microscopy in RCC cells deficient of the VHL tumor suppressor gene (786-O and A498) and normal renal epithelial (HK2) cells." (PMID 29051480, 2017). "For example, NOX4 senses oxygen, produces ROS and is associated with tumor growth, and NOX5 and NCF2 produce superoxide." (PMID 26590118, 2016). "We propose that adipocytes increase pro-inflammatory cytokines, adipokines, and other endocrine signals to activate NOX4, promoting the generation of intracellular ROS, leading to DNA damage, a DNA damage response, DNA mutation and subsequent fibroid tumor development and growth." (PMID 37628676, 2023). "To conclude, our study suggests that NOX4 is associated with both ferroptosis and tumor immunity, and may be a biomarker associated with the prognosis and tumorigenesis of CC and a potential target for immunotherapy of CC in the future." (PMID 36249057, 2022). "To conclude, our study suggests that NOX4 is associated with both ferroptosis and tumor immunity, and might be a biomarker associated with the carcinogenesis, prognosis of CC and a potential target of CC immunotherapy." (PMID 36249057, 2022). "In contrast, recent studies found tumor-promoting effects of Nox4 deficiency." (PMID 35348887, 2022). "Therefore, the loss of NOX4 favors an epithelial to amoeboid transition, contributing to tumor aggressiveness." (PMID 34571961, 2021). "Notably, Nox4 mRNA levels were highest in the tumor‐associated stroma with ∼30% to >60% of cells positive for Nox4 staining." (PMID 29441570, 2018). "Therefore, we sought to examine if inhibiting Nox4 would be a potential approach to suppress the formation of a tumor that originates from tuberin-deficient cells." (PMID 29491408, 2018). "Furthermore, NOX4 is associated with tumor growth and the prevention of apoptosis in the presence of growth factors in several malignancies." (PMID 29065504, 2017). "Therefore, loss of NOX4 increases actomyosin levels and favours an epithelial to amoeboid transition contributing to tumour aggressiveness." (PMID 27941881, 2017).
tumor (continued). "We speculate that the NOX4 mutation may have increased the reactive oxygen species and mutation rate in the tumor microenvironment." (PMID 25729435, 2015). "Therefore, we might speculate an interaction between NOX4 and the tumor microenvironment even in TC through the recruitment of tumor-associated inflammatory cells, including TAMs." (PMID 37891977, 2023). "Tumor-derived NOX4 promoted secretion of GM-CSF, which was established through in vivo functional assays as the key factor responsible for neutrophil recruitment." (PMID 42157942, 2026). "Combined EGFR inhibition and NOX4-mediated ROS suppression would provide synergistic anti-tumor effects in resistant cancers." (PMID 41562694, 2026). "Tumor-derived NOX4 drives GM-CSF-dependent neutrophil recruitment, leading to metabolic reprogramming and immunosuppression in GC." (PMID 42157942, 2026). "In KRAS-driven tumor cells, NOX4 activity enables cells to adapt to oxidative stress, thereby promoting tumor progression." (PMID 41328353, 2026). "In experimental models, NOX4 deletion reduces these tumor-suppressive checkpoints, enhances survival of genomically unstable hepatocytes, and favors a shift toward protumorigenic M2 macrophage polarization." (PMID 41516036, 2025). "Subsequently, THN‐mediated radiosensitization stimulated tumor cells to produce hydrogen peroxide (H2O2) by upregulating NOX4 protein, promoting the chemodynamic process of Hemin reacting with H2O2 to continuously produce hydroxyl radicals." (PMID 40534404, 2025). "The heightened expression of NOX4 in endothelial cells suggests its potential as a marker for tumor development." (PMID 39859485, 2025). "Cell-cell communication is also of importance in shaping the TME, where metastatic survival depends on specific signaling (through CXCL12-CXCR4) between GPX4+ tumor and NOX4+TGFB1+CXCL12+ CAFs." (PMID 41450739, 2025). "By using CAF-rich murine tumor models with a T-cell exclusion phenotype, the role of NOX4 inhibition in normalizing myoCAFs to a quiescent phenotype and overcoming T-cell exclusion by increasing intratumoral T-cell infiltration has been revealed." (PMID 40469190, 2025). "We then analyzed NOX4 protein levels in multiple tumor cells and primary tumor samples, and found NOX4 expression was markedly elevated in MYC(N)-high tumor cells and tumor samples." (PMID 38493213, 2024). "The positive correlation between NOX4 expression and immune cell infiltration levels in the tumor microenvironment adds complexity to its role in cancer progression." (PMID 38663913, 2024). "Previous studies have shown that aberrant expression of NOX4 in tumor cells leads to elevated cellular ROS levels, promoting tumorigenesis." (PMID 38663913, 2024). "IFNγ can contribute to increased anti-tumor activity of CD8+ T cell response and the DNA damage response induced by NOX4 can lead to activation of cell cycle checkpoints that arrest proliferation and/or induce apoptosis of tumor cells." (PMID 39588838, 2024). "Both PGC‐1α and Nox4 expression were measured from the gastrocnemius muscle from the tumor group and found to be unchanged compared to the non‐tumor group." (PMID 38946587, 2024). "Investigating the relationship between NOX4 expression and immune cell infiltration in the tumor microenvironment revealed a significant positive correlation with six immune cell types in most tumor types, excluding DLBC, UVM, THYM, and TGCT." (PMID 38663913, 2024). "The loss of NADPH oxidase 4 (NOX4) in HCC induces MR in a nuclear factor erythroid 2-related factor 2 (Nrf2)/Myc-dependent manner, promoting tumor progression and making this tumor suppressor function a targeted therapy." (PMID 39484162, 2024). "For example, TGF‐β1 can activate NADPH oxidase 4 (NOX4), which allows NADPH to carry out electron transfer, causing accumulation of large amounts of ROS in tumour cells." (PMID 38652105, 2024).
tumor (continued). "It seeks to provide insights for future experimental research and aid in the clinical translation of NOX4 as a tumor biomarker, thereby improving the diagnosis, prognosis, and selection of treatment options for cancers." (PMID 38663913, 2024). "Other studies have shown that miR‐99a inhibits the invasion and migration of tumor cells by targeting NADPH oxidase 4 (NOX4)‐mediated reactive oxygen species (ROS) generation pathway." (PMID 38602270, 2024). "The results of these enrichment analyses do not seem to provide a better understanding of the mechanism of NOX4 in the tumor microenvironment." (PMID 36874093, 2023). "At this stage, the research results on the function of NOX4 in cellular metabolism and the signal transduction in the tumor microenvironment are widely recognized, at the cellular level and in mouse tumor models." (PMID 36874093, 2023). "Consistently, we discovered that NOX4 knockdown significantly reduced proliferation, colony formation, and tumor proliferation in mice compared to the control group." (PMID 37626693, 2023). "The mRNA and protein expression of SIRT1 and NOX4 was significantly downregulated in the LLC tumor groups compared to the control group, as well as FOXO1 and FOXO3a in vitro." (PMID 37190306, 2023). "The expression of KEAP1, NFE2L2, and NOX4 were generally higher than normal level of body in more than 20 tumor tissue samples." (PMID 36627482, 2023). "The increased expression of Nox4 is likely the closest indicator of a gene expression shift mediating the lactate adaptation process as Nox4 has been shown to encourage tumor growth in anaerobic environments." (PMID 37628627, 2023). "In particular, we dissect the contribute of NOX1, NOX2, and NOX4 enzymes in the modulation of cellular metabolism and highlight their potential role as a new therapeutic target for tumor metabolism rewiring." (PMID 36768405, 2023). "Tumors from the NOX4-overexpressing group formed more rapidly and had significantly higher tumor volumes and weights when compared to the control group." (PMID 37626693, 2023). "A study showed that NOX4 expression strongly correlated with tumor size, lymphatic metastasis, vascular invasion and a poor prognosis in GC patients, and suppressed cancer-associated fibroblasts-mediated immunotherapy." (PMID 38021154, 2023). "Molecular studies based on the cellular level and tumor models in animals have demonstrated that NOX4 plays an important role in tumor metabolism and microenvironment regulation." (PMID 36874093, 2023). "RT-qPCR analysis revealed that NOX4 function was overexpressed in tumor cells from humans (MDA-MB-231 and MCF-7) as compared to MCF-10 A control lines." (PMID 38012557, 2023). "We found that a mature tumor marker, NOX4, play different roles in different clinical subgroups by immunohistochemical analysis and clinical data." (PMID 36874093, 2023). "Collectively, all results further strongly indicate that NFE2L2 and NOX4 play important roles in tumor immunity." (PMID 36627482, 2023). "CHAC1, in addition to NOX4 and GPX4, is considered to be a hallmark of ferroptosis and has been reported to be involved in tumor cell death via the induction of ferroptosis." (PMID 37371096, 2023). "NOX4 plays an important role in tumor microenvironment and has a significant relationship with the occurrence, development and drug resistance of tumor." (PMID 36874093, 2023). "In this study, the tumor growth rate was significantly delayed after the application of the NOX4 inhibitor GKT137831." (PMID 37670970, 2023). "Numerous studies have shown that NOX4 plays a crucial role in tumorigenesis and tumor progression by supporting cancer cell transformation, proliferation, migration, invasion, and epithelial–mesenchymal transition (EMT)." (PMID 37626693, 2023).
tumor (continued). "The ROS produced by NOX4 is involved in a variety of biological functions, including signal transduction, cell differentiation and tumor cell growth, and NOX4 plays an important role in the process of ferroptosis." (PMID 35610340, 2022). "It is demonstrated that NOX4 also serves as a mitochondrial energetic sensor engaged in reprogramming tumor metabolism for drug resistance." (PMID 35646942, 2022). "Specifically, gallbladder CAFs elevate vasculogenic mimicry formation and tumor growth through increasing NOX4 expression via activating IL-6-JAK-STAT3 signaling." (PMID 35646942, 2022). "Many studies have shown that NOX4 and its derivatives ROS are closely related to tumorigenesis or carcinogenesis, cancer cell proliferation, tumor metastasis, invasion, DNA damage, and anticancer cell apoptosis." (PMID 35528617, 2022). "Further investigation would be required to expand our understanding of NOX4-responsive stresses among various tumor microenvironments and elucidate the detailed mechanisms of adapting to these stresses." (PMID 35396551, 2022). "We also determine primary tumor growth and metastasis of implanted tumor cells using a stable Nox4-/- syngeneic mouse model." (PMID 35836253, 2022). "So far, the understanding of NOX4 in tumor microenvironments remains fragmentary, but it can be inferred that NOX4 is required for microenvironments-stressed PTC cells that need ROS and glycolysis to serve as the major bioenergetic pathway." (PMID 35396551, 2022). "Significantly higher levels of Nox4 mRNA expression were seen in correlation with the tumor grade in the stroma region." (PMID 35836253, 2022). "Numerous studies have elucidated that NOX4 gets involved in the regulation of tumor proliferation, metastasis, therapy resistance, tumor-stromal interaction and dysregulated tumor metabolism." (PMID 35646942, 2022). "The pathway through which TGF-β drives EMT and cellular migration in breast epithelial normal and tumor cells partially rely on the NADPH oxidase 4 (NOX4), an enzyme, that is a major source of intracellular ROS." (PMID 36226048, 2022). "The authors demonstrated that Nox4-generated ROS are critical for inducing DNA damage response upon exposure to carcinogens and that depleting Nox4 promoted genetic instability and tumor initiation." (PMID 35836253, 2022). "Our group demonstrated that the accumulation of ROS in OC cells was attributed to H2O2 increased levels induced by NOX4, identifying an endogenous mechanism for the overproduction of ROS and alteration of intracellular signaling in OC tumor development." (PMID 35743145, 2022). "NOX4-induced ROS can also protect tumor cells from apoptosis via AKT-dependent phosphorylation of apoptosis signal-regulating kinase 1, thus NOX4 blockade resulting in cell apoptosis." (PMID 35646942, 2022). "Numerous studies have shown that NOX4 plays a crucial role in tumorigenesis and tumor development by supporting cancer cell transformation, proliferation, migration, invasion, and epithelial–mesenchymal transition (EMT)." (PMID 35646942, 2022). "With the acknowledgements to the role of NOX4 in tumor occurrence and development, NOX4 is an emerging therapeutic target for development of anti-tumor drug." (PMID 35646942, 2022). "The correlation between NOX4 and tumor immune infiltrating was explored by CIBERSORT and spearman correlation analysis." (PMID 36249057, 2022). "Multiple studies have found that the upregulation of NOX4 can promote the occurrence and metastasis of tumours." (PMID 35023280, 2022). "We also observed that intracellular ROS was significantly decreased in sericite-treated mouse neoplasms, along with reduced phosphorylation of p66shc and reduced mRNA expression of p22phox and NOX4, which are upstream regulators of p66shc." (PMID 36199546, 2022). "The upregulation of HIF-1α and VEGF are positively correlated with NOX4-derived ROS production in OC cells and promotes angiogenesis and tumor growth." (PMID 35743145, 2022).
tumor (continued). "Even though NOX4 inhibitors have been evaluated in multiple cancer types for its anti-tumor activity in vitro and vivo, it is still required to explore deeper to identify the cancer types that can be effectively treated with NOX4 inhibitors." (PMID 35646942, 2022). "Taken together, NOX4 displays great significance in wide variety of cancers, indicating great potentials of NOX4 inhibitors as anti-tumor therapy." (PMID 35646942, 2022). "In this study, we have further investigated the influence of Nox4 on fibroblast activation and their tumor-promoting function." (PMID 35836253, 2022). "Other studies present NOX4 and ITGA3 as relapse risk markers with important clinical interest, in order to understand how the mechanism of tumor’s progression to metastasis is activated." (PMID 34073426, 2021). "We constructed a Pan-Cancer dataset from 23 tumor types and explored NOX4 expression patterns in relation to EMT and patient survival." (PMID 33557266, 2021). "Despite NOX1 and NOX2 seeming to be inducers/promoters of HCC, recent findings postulate NOX4 as a tumor suppressor." (PMID 34571961, 2021). "In conclusion, we present evidence that the NOX4-autophagy signaling axis plays a role in the remodeling of the tumor environment that resulted from the interaction of cancer cells with TB-educated PMCs." (PMID 33567693, 2021). "Many of the mutated genes, such as NOX4 and PPP1R1A, have been implicated in tumour progression and/or metastasis." (PMID 34299215, 2021). "Preliminary immune-histological and gene expression surveys of human primary tumor samples have revealed elevated NOX4 protein or transcript levels relative to adjacent normal healthy tissues in several tumor types." (PMID 33557266, 2021). "Other in vitro studies using established tumor lines or primary cell cultures support roles for NOX4 in angiogenesis and tumor cell proliferation or suppression of apoptosis." (PMID 33557266, 2021). "Tumor macrophages appear to be a source of NOX2, whose association with genetic programs of cancer progression emulate that of NOX4." (PMID 33557266, 2021). "The mouse tumor xenograft studies showed that Nox4 was highly expressed in the cycling hypoxic areas within the tumor microenvironment." (PMID 33535436, 2021). "The results showed that the expression of SP1, KEAP1, AIFM2, and NOX4 all increased in tumor tissues." (PMID 34745421, 2021). "Our results showed that the expression levels of NOX4 were significantly higher in the tumor tissues compared with adjacent tissues." (PMID 34209278, 2021). "In support to its potential tumor suppressor role, NOX4 inhibits liver cell proliferation either under physiological conditions or during tumorigenesis." (PMID 34571961, 2021). "Although some studies have shown that pharmacological/genetic inhibition of NOX4 can inhibit tumor development at the cellular level or in animal models, the effectiveness in human still needs further clinic trial." (PMID 34930338, 2021). "mRNA vaccines encoding these tumor antigens (THBS2, FSTL3, TNNT1, BGN, CTHRC1, and NOX4) induce a cell-mediated immune response and humoral immune response that are beneficial for efficient clearance of cancer cells." (PMID 35127707, 2021).